CD44 (CD44 molecule (IN blood group))
Diseases named in the same sentence as CD44 in open-access papers (continued):
Sharing a sentence is not in itself a finding about the gene and the disease.
tumor (continued). "Analysis of MC38 tumor-bearing mice treated with the Bpmel-SIY-OVAII cell adjuvant revealed a sustained increase in the proportion of CD27− CX3CR1+ and CD62L− CD44+ effector CD8+ T cells in the DLN as well as more significant infiltration of CD8+ T cells in the tumor site." (PMID 41348109, 2026). "As a result, the two Gemini-like NPs in hydrogel cut CAF-secreted CCL2 by 72%, reduced CD44+CD133+ CSCs by 68%, and tripled intratumoral granzyme-B+ CD8+ T cells, yielding almost complete tumor regression in 90% of mice (n = 10), which achieved a remarkable regression of the chemo-resistant tumors." (PMID 41355964, 2026). "Similarly, CD44 and CD133 were chosen as representative CSC markers, as their expression denotes self-renewal capacity and tumor-initiating potential." (PMID 41583390, 2026). "CD44, a broadly expressed CSC marker, serves as a central regulator of cell adhesion, migration, stemness maintenance, and immune modulation, and represents a promising therapeutic target in tumor progression and treatment resistance." (PMID 41510165, 2026). "Additionally, we analyzed the expression of CSC genes in these tumours and found that the expression levels of CD133, CD44 and ALDHA1 were consistent with the effects of FOXO3a/miR4259 signaling on LDHA expression." (PMID 39930542, 2025). "Therefore, next the expression levels of CD44 and CD109 were also determined in the tumour specimens from these patients at different cut-off values." (PMID 40227788, 2025). "We also evaluated CD44 and ALDH1 expression in patient tumour samples." (PMID 40282522, 2025). "Furthermore, the CD44‒SPP1 axis is vital for cell‒cell communication and exerts significant immunomodulatory effects within the tumor microenvironment (TME)." (PMID 40524208, 2025). "It uses a machine learning algorithm to compute a risk score for distant recurrence over a timeline of five years with the inputs from IHC gradings of five biomarkers (CD44, ABCC4, ABCC11, N-Cadherin, and pan-Cadherin) along with three clinical parameters (node status, tumor size, and tumor grade)." (PMID 39944436, 2025). "By comparison, M-tumours contained mostly areas that were CD104low CD44high lacking E-cad/VIM with minor CD104/CD44/E-cad/VIM positive clusters." (PMID 40764669, 2025). "Mechanistically, tumor cells exhibit strong adhesive properties and overexpress membrane proteins, such as CD47, CD44, and various integrins, which enable immune evasion, intercellular adhesion, and the recruitment of circulating cells—processes that contribute to tumor progression and metastasis." (PMID 40624508, 2025). "This points to a nonuniform response of tumor cells from different cancers upon interaction of CD44 with the same receptor." (PMID 40114966, 2025). "In this study, we investigated whether HER2-specific CAR NK cells display the same efficacy against both trastuzumab-sensitive (CD44−) and trastuzumab-resistant (CD44+) HER2+ tumor lesions." (PMID 40075578, 2025). "Additionally, through binding with CD44 and integrins, SPP1 enhances ECM remodeling, increases tumor stroma stiffness, and supports immune evasion." (PMID 41391064, 2025). "Moreover, tumor cells were reprogrammed to express various stem cell markers (e.g. ALDH1A1, CD44, CD133, and SOX2), which are involved in self-renewal, stemness acquisition, and CRPC transformation." (PMID 39711287, 2025). "Importantly, the ratios of Treg cells to CD44+ CD8+ T cells both in the dLNs and tumor-infiltrating lymphocytes were remarkably reduced in the combination treatment group." (PMID 40290124, 2025). "Tumor growth and metastasis may be prevented by targeting OPN’s interactions with integrins, CD44, or through downstream signaling pathways." (PMID 40647541, 2025).
tumor (continued). "Surface modifications, such as hyaluronic acid or antibodies targeting CD44 or EGFR, enable active tumor targeting, while stimulus-responsive nanoplatforms (e.g., pH- or GSH-sensitive) ensure controlled release of Sonosensitizers and immunostimulants within the TME." (PMID 41451226, 2025). "The fluorescence staining results for CD44, PTN and Collagen revealed that CD44high-PTNhigh tumor cells was observed not only specifically at the leading edge, but also near fibroblasts infiltrated within tumor microenvironment." (PMID 40069574, 2025). "Additionally, dual staining revealed spatial proximity between the CAF marker α-SMA and tumor stem cell markers CD133 and CD44." (PMID 40735647, 2025). "Additionally, we revealed that MCPIP1 RNase activity regulates the expression of the stemness markers CD44 and CD133 and the phosphorylation of the c-Met receptor in tumor tissue samples." (PMID 39815326, 2025). "Targeting the SPP1–CD44 axis with anti-SPP1 or anti-CD44 antibodies, either alone or in combination with anti–PD-1, restored T cell function in vitro and significantly reduced tumor burden in mouse models." (PMID 41425545, 2025). "Both CD44 and DEC1 are pivotal in tumor biology, each contributing through distinct but often overlapping mechanisms, and together, they influence cancer stemness, metastasis, and resistance to therapy, highlighting their potential as therapeutic targets in cancer treatment." (PMID 40005368, 2025). "Moreover, we performed immunohistochemical staining for the stem cell markers CD44 and CD133 in tumor tissues." (PMID 39523731, 2025). "Similar to our previous finding for the KPC-4545 model, all three clusters of CAFs appeared to be the main source of growth factors, including TGFβs, FGFs, and VEGFs which bind to receptors including CD44, TGFβreceptors, and ITGs in the untreated KPC-3403 tumor." (PMID 39948655, 2025). "In contrast, CD44 staining was present in three smokers and in five never-smokers and localised to tumour cells and in some instances to the tumour stroma." (PMID 40282522, 2025). "No papers presented data on CD44 expression in the entire tumor area nor in the stroma in the subgroup of TNBCs." (PMID 39904885, 2025). "The authors analyzed the effect of polyphenols from blueberries on two microRNAs: miR-210, an oncogenic molecule able to maintain the CSC phenotype and induce EMT, and miR-145, a tumor suppressor molecule that reduces tumor sphere formation and decreases the levels of CD133, CD44, and OCT4." (PMID 39859345, 2025). "Mechanistically, ADAM10-mediated shedding generates sGPNMB that drives tumor cell migration and invasion through MMP activation, while simultaneously shaping an immunosuppressive TME marked by M2 macrophage infiltration and CD44+ immune cell accumulation." (PMID 41180454, 2025). "As a transmembrane glycoprotein implicated in cell adhesion, cytoskeletal remodeling, and signal transduction, CD44 synergizes with CD147, particularly within hyaluronan-enriched microenvironments to coordinate downstream signaling pathways involved in tumor progression." (PMID 41479915, 2025). "To investigate whether the different tissue penetration capacities result in different efficacies in tumor elimination in vivo, we established subcutaneous HER2+/CD44+ JIMT-1.ffLuc xenografts in NSG mice." (PMID 40075578, 2025). "In addition, the expression of CD62L and Ly108 in the CD44+PD-1+CD8+ TILs, and the proportion of Ly108+ Tpex cells, especially CD62L+CD8+ Tpex cells, significantly increased in the mouse B16 hormonal tumor model compared with the PBS control group." (PMID 40236705, 2025). "In 38% of the cases, the tumor cells coexpressed CD24 and CD44." (PMID 40647395, 2025). "For example, CD44 is highly expressed in muscle-invasive tumors and drives EMT, invasion, and angiogenesis, whereas ALDH1A1 marks a subpopulation with enhanced tumorigenicity and correlates with tumor progression, recurrence and poor survival." (PMID 40635786, 2025).
tumor (continued). "•sTN58 efficiently hampers tumor growth and lung metastases by blocking CD44-mediated signaling, without inducing toxicity." (PMID 40342488, 2025). "The tumor sphere formation assay showed that EXOSC10 deletion declined the sphere formation rate in Huh-7 and Hep3B cells, as well as impaired the expression of OCT4 and CD44 proteins, indicating the inhibition of cancer cell stemness after EXOSC10 knockdown." (PMID 40221814, 2025). "Additionally, the fluorescently labeled scFv‐SNAP‐tag immunoconjugates have demonstrated their capacity to profile South African TNBC tumor biopsies for clinically relevant EGFR, CSPG4, and CD44 biomarker expression." (PMID 40970572, 2025). "Also, there was a significant positive correlation between the depth of tumor invasion and the expression of CD133+, as well as the co-expression of CD44+/CD133+, CD166+/CD133+ and CD133+/CD166+/CD44+ (p ≤ 0.05)." (PMID 41303421, 2025). "FASN silencing reduced spheroid formation, in vivo tumor growth, and CD133+CD44+ cells." (PMID 40901481, 2025). "Furthermore, CD44-ECD-mediated homophilic cell-to-cell adhesion is well-documented in tumors and can facilitate tumor cell aggregation and metastasis." (PMID 41049281, 2025). "Collectively, these results indicate that FASN is highly expressed in colorectal CSCs and is crucial for maintaining CSC characteristics, promoting spheroid formation, in vivo tumor growth, and preserving the CD133+CD44+ CSC population, thus contributing to CRC progression." (PMID 40901481, 2025). "There was no data on CD44/CD24 expression in TNBC patients with special attention to tumor stroma nor in the entire tumor area." (PMID 39904885, 2025). "Further investigation revealed that IL-8 promotes tumor stemness in ICC, accompanied by upregulation of CD133, CD44, and OCT-4 expression, while either SB225002 or JSH-23 could inhibit the effect of IL-8." (PMID 40008905, 2025). "Interestingly, the expression of such markers is tumor subtype specific: CD44+CD−/low lineage and ALDH+ are abundant in breast CSCs, CD133+ for colon, brain and pancreas, CD44+ for head and neck and cervix, CD90+ for liver CSCs and head and neck cancers." (PMID 40141362, 2025). "In our research, the co-expression of CD44 and CD133 markers, as the most frequently analyzed putative cancer stem cell markers, was found to range from 0.2% to 55.2% (median 1.7%) in cells of tested tumor tissue samples." (PMID 41303421, 2025). "Using the CD44 marker, only a few interstitial inflammatory cells resembling lymphocytes became labeled, and no tumor cells were labeled." (PMID 40941427, 2025). "CD44, MMP-2, MMP-9, N-cadherin, and ZEB-2 were selected because they complementarily represent the three main axes of early tumor invasion: cell adhesion (CD44 and N-cadherin), extracellular matrix degradation (MMP-2 and MMP-9), and epithelial–mesenchymal transition (N-cadherin)." (PMID 40940940, 2025). "Many CSC surface markers (such as CD133, CD44) are also expressed by normal stem cells or other non-malignant cell types, raising concerns regarding on-target off-tumor toxicity." (PMID 40771808, 2025). "Tumor and matched adjacent noncancerous tissues were collected and analyzed for the expression of CD44, CD90, CD133, and EpCAM using immunohistochemistry (IHC)." (PMID 40791212, 2025). "As ECM stiffness generally regulates tumor progression through its receptors, we systematically screened several common ECM-sensing receptors (ITGB1, CD44, Piezo1, Piezo2, YAP1, Syndecan1, and DDR1) via siRNA knockdown, and confirmed the knockdown efficiency by conducting qRT-PCR analyses." (PMID 40685383, 2025). "Thus, artificial suppression of SOX9 in PANC-1 cells decreased the number of cells carrying CD44 and CD24 markers, as well as decreased the ability of the cells to form spheres (sphere formation rate) and to initiate tumor in nude mice." (PMID 40141294, 2025).
tumor (continued). "Additionally, CD44-targeting oil-core polymer nanocapsules and PEG-PLA nanoparticles functionalized with tumor-homing F3 peptide exhibit high tumor accumulation, leading to greater drug retention and improved chemotherapy efficiency." (PMID 40286158, 2025). "In addition, our study revealed that the incidence of CD133+, CD44+/CD133+, CD166+/CD133+ and CD133+/CD166+/CD44+ cells in OSCC, increased significantly with the increase in tumor invasion depth (p ≤ 0.05), implying the positive correlation." (PMID 41303421, 2025). "Moreover, hypoxia can enhance the stemness of tumor cells by upregulating CSC markers such as CD133, CD44, SOX2, OCT3/4, and NANOG, thereby activating the EMT process and promoting the formation of VM." (PMID 41019994, 2025). "Our study also investigated whether there is a correlation between the expression of analysed CD44, CD133 and CD166 markers and certain clinico-pathological parameters, including sialometry, depth of tumor invasion and tumor dimensions." (PMID 41303421, 2025). "Besides, the results of tumor microenvironment analysis suggested that ANXA5, STAT1, CD44, CAV1, and ANXA2 expression was positively correlated with the infiltration of B cell, CD8+ T cell, CD4+ T cell, macrophages, neutrophils, and dendritic cells." (PMID 40607003, 2025). "Finally, PRDX2 KO reduced the expression of the CD44 stem cell marker in tumors, supporting the role of PRDX2 in stemness and tumor initiation." (PMID 40932790, 2025). "CD44 is a putative cancer stem cell biomarker and may interact with EGFR, CD109, and EGFRvIII to facilitate the tumour progression and resistance to therapies." (PMID 40227788, 2025). "Our findings, to some extent, support previous findings, highlighting a complex regulatory interaction between CAFs and CD44+ CRC cells, which may ultimately drives tumor progression." (PMID 40069574, 2025). "Moreover, CD44+ cells interact with stromal cells to promote angiogenesis by secreting VEGF, thereby supporting tumour growth and distant colonisation." (PMID 40665579, 2025). "Drugs that target CSCs, such as metformin, may exhibit efficacy similar to anti-angiogenic therapies, which is due to the reduction in the proportion of CD44+/CD117+ CSCs and the alleviation of hypoxia in the tumor microenvironment." (PMID 40804837, 2025). "ST data further confirmed the spatial co-localization of tumor and immune cells, as well as the expression of co-inhibitory ligand–receptor pairs, such as SPP1/CD44 and MIF/CD74, highlighting the mechanism by which tumor cells promote immune escape through the expression of co-inhibitory factors." (PMID 40867511, 2025). "Activation of tumor-infiltrating T cells was unchanged as surface expression of the activation marker CD44 was not affected by MC38-expressed LRRC8A." (PMID 41419196, 2025). "Finally, based on the target capability of HA with CD44 over‐expressed in cancer cells, the AHA@MnP/siPD‐L1 NPs exhibited significant accumulation at tumor sites with good biosafety and demonstrated potent antitumor effects against 4T1 tumors." (PMID 40585771, 2025). "Therefore, dual-targeting strategies against CD44 and HER2 can more comprehensively cover different subtypes of tumor cells and improve the precision and effectiveness of treatment." (PMID 40942197, 2025). "In our analysis, we observed that the chemo-naïve basal tumor samples had high CD44 and low CD24 expression (CD44+/CD24−/low phenotype), which could be interpreted as BCSC-enriched, consistent with previous studies on chemoresistant cohorts." (PMID 40362201, 2025). "One subpopulation expressed CD44 + CXCR3 + CXCR4 + PRF1 + and GZM family genes, while the other expressed XCL1 + NCAM1 + GNLY + and KIR family genes, suggesting that these T cells possess a robust capacity to mediate tumor cell apoptosis." (PMID 40411616, 2025).
tumor (continued). "Considering that CD44 and TNFRSF1A primarily function as receptors, while ANXA1 can participate in regulating the tumor immune microenvironment as a secreted protein, we focused on whether NRF2 regulates the tumor immune microenvironment through ANXA1." (PMID 40583858, 2025). "While CD44 was not identified as an extracellular target of caspases by our MS analysis, it is otherwise a common target of other sheddases in the tumor microenvironment." (PMID 40331965, 2025). "Moreover, silencing CD70 downregulated stem-related markers (CD44 and SOX-2), inhibited tumor growth and migration, promoted immune suppression by attracting monocyte-derived M2 macrophages, further highlighting its therapeutic potential." (PMID 41233805, 2025). "Subsequent CellChat analysis revealed enhanced interactions between ACACA-high tumor cells and CD8+ T cells, primarily via secreted signaling pathways like the macrophage migration inhibitory factor (MIF) axis (MIF-CD74+CXCR4, MIF-(CD274+CD44))." (PMID 41169354, 2025). "This and other studies highlight the importance of understanding the CD44-HA interaction within GBM, since the application of HA scaffolds adjacent to these tumours could promote growth and invasive capacity." (PMID 39852021, 2025). "Molecular studies demonstrated treatment of SKOV cells with MDA-MB-231-derived exosomes increased miR-454 expression in CD44 + /CD133 + SKOV cells through the activation of the Wnt pathway via proline rich transmembrane protein 2 binding and increased stemness in vitro and tumor growth in vivo." (PMID 38796525, 2024). "Therefore, this study assessed the expression of FAK, ILK, CD44, HIF-1α, and Ki67 in EC patients after neoadjuvant radiochemotherapy followed by tumor resection (NRCHT+R) and correlated these markers with the MTE." (PMID 38727811, 2024). "In EC, CD44 and CD133 are also used as surface markers of tumor stem cells in most studies." (PMID 38706601, 2024). "We also revealed that lysyl oxidase–like protein 2 (LOXL2), a well-known regulator of tumor, is an endogenous ligand binding to the PEAR1-EMI domain and facilitating PEAR1 Ser891 phosphorylation, which is essential for the binding of PEAR1 to CD44." (PMID 39145451, 2024). "Cytoplasmic CD74 expressed on APCs functions as an antigen-presenting partner, whereas the overexpression of cell surface CD74 on tumor cells or immune cells serves as MIF receptor, promoting the release of pro-inflammatory and pro-angiogenic factors along with CD44 and CXCR4 ligands." (PMID 38280003, 2024). "We evaluated the frequency of CD44- and CD122-expressing memory CD8+ T cells and found that the majority of long-lived Nrf2−/−OT-I cells had the CD44hiCD122hi phenotype compared to the OT-I or Nrf2TgOT-I group in both tumor models." (PMID 39169624, 2024). "Interestingly, while Dac treatment did not alter the growth of MC38 tumors in NOD/SCID mice, in C57BL/6 J mice it significantly suppressed the growth of MC38 tumors, reduced TGF-β1 expression in tumor tissue, and activated TME-derived CD44+CD8+ T cells." (PMID 38971819, 2024). "Absence of staining for CD44 was observed in the normal seminiferous tubules adjacent to tumor lesions as well as in the interstitial connective tissue in the interlobular septa around the normal seminiferous tubules." (PMID 38796656, 2024). "When examining the phenotype of CD27+Ly6C− and CD27+Ly6C+ γδ T cells in KP and KB1P tumor-bearing mice, we found that CD27+Ly6C+ γδ T cells expressed higher levels of CD160, NKG2A, IFNγ, and CD44 in spleen, LN, and lung, analogous to observations made in tumor-naive mice." (PMID 38816652, 2024). "However, the percentage of CD44+ CD8+ and CD134+ CD8+ T cells in tumor were increased in cKO mice compared to WT mice." (PMID 38994031, 2024).